CD4 (CD4 molecule)
Diseases named in the same sentence as CD4 in open-access papers (continued):
Sharing a sentence is not in itself a finding about the gene and the disease.
COVID-19 (continued). "The CD4+ T memory response was detected in all recovered patients from COVID-19, and 70% of patients had established CD8+ T memory response to SARS-CoV-2, lasting for more than 2 months." (PMID 35011632, 2021). "Specifically, PD-L1 upregulation is induced by SARS-CoV-2 in infected epithelial cells and is dysregulated in several types of immune cells of COVID-19 patients including monocytes, neutrophils, gamma delta T cells and CD4+ T cells." (PMID 34163490, 2021). "There is no doubt that it is necessary to determine if these cytotoxic CD4 T cells have some role in tissue damage and thrombotic complications in COVID-19." (PMID 33777054, 2021). "A reduction of lymphocytes, especially in the CD4+ T cell subgroup, has been reported to correlate with COVID-19 severity." (PMID 33967773, 2021). "COVID-19 patients are also reported to show CD4+ lymphopenia; CD8+ lymphopenia; and higher levels of cytokines such as interleukin (IL)-6, IL-10, and tumor necrosis factor alpha (TNF-α)." (PMID 34360684, 2021). "As per adaptive immune parameters, the frequencies of plasmablasts and activated CD8+ and CD4+ T cells were increased in severe COVID-19 patients." (PMID 34745145, 2021). "For the symptomatic COVID-19 patients, 27/71 (35.23%) and 36/71 (50.70%) of the samples also developed virus-specific specific CD4+ T cells and CD8+ T cells, respectively." (PMID 33741972, 2021). "Transferring CD4+ T cell populations to T helper cell 2 (Th2) phenotypes during pregnancy (a response that promotes humoral rather than cellular immune responses), reduced T helper cell 1 (Th1) reactivity may lead to reduced clearance of infected cells, increasing susceptibility to COVID-19." (PMID 34458162, 2021). "Surrounding the brain vasculature in COVID-19 patients, we detected CD4+ and CD8+ T cells, as well as CD68+ macrophages, indicative of perivascular inflammation, rather than widespread neuroinflammation in the brain parenchyma." (PMID 34769052, 2021). "Although it is currently difficult to determine the exact antibody levels and duration after infection, evidence suggests that individuals who have recovered from COVID-19 have developed a favorable immune response regarding their memory CD4+ and CD8+ T cells." (PMID 34681059, 2021). "It has been reported that the activated CD38+HLA-DR+, CD8+ T cells, and CD38+HLA-DR+ CD4+ T cells that respond to virus infection are transiently increased in COVID-19 patients." (PMID 35011632, 2021). "The COVID-19 patient with ARDS also shows increased chemokine receptor 6 (CCR6)+ T helper 17 (Th17) cells which are derived from CD4+ T cells." (PMID 33632295, 2021). "The percentage of IFN-γ producing CD4+ T cells was increased in severely affected COVID-19 patients, in line with the previously reported contribution of IFN-γ to the cytokine storm in SARS patients." (PMID 34867933, 2021). "A few studies on SARS-CoV-2-specific T-cell responses and their role in protective immunity found that recovered patients with COVID-19 show CD4+ and CD8+ memory responses to SARS-CoV-2." (PMID 34780495, 2021). "When the two megapools were combined to assess the overall CD4+ T cell reactivity OTD-CoV-2pos subjects showed a significantly higher reactivity when compared to both OTD-CoV-2neg or severe COVID-19 patients." (PMID 34858405, 2021). "Next, we investigated if MILD COVID-19 patient-recovered exosomes were capable of favoring CD4+ T-cell activation driven by other APC sources." (PMID 35111156, 2021). "Kinetics of immune response from mild, moderate to severe COVID-19 patients ranges from augmented humoral and cellular immunity to lymphopenia affecting CD4+ T cells, CD8+ T cells, B cells and natural killer cells." (PMID 33435561, 2021). "Lymphocytopenia is a common feature in patients with severe COVID-19, accompanied by a sharp decrease in the number of CD4 and CD8 T cells, B cells, and natural killer (NK) cells." (PMID 34451952, 2021).
COVID-19 (continued). "The COVID-19 spike protein can then be presented to CD4+ T cells once they are processed, and the cells then convert into memory T cells, and CD4 T cells aid B cells with the conversion into plasmocytes, which allows the production of antibodies." (PMID 34681059, 2021). "We found that disease in this model largely mirrored that observed in RhM but with unique immune features, such as pulmonary infiltration of CD4+ T cells that exhibit antiviral and cytotoxic functions, as is seen in COVID-19 patients." (PMID 34929014, 2021). "As for memory phenotype, the majority of SARS-CoV-2-specific CD4+ T cells in COVID-19 convalescents were identified as central memory T cells when stimulated with MegaPools (overlapping or prediction-based peptides covering the SARS-CoV-2 proteome)." (PMID 34452355, 2021). "Present study revealed independent predictors for severe COVID-19 and found CD4+ T cell was mainstay of immunity response to severe SARS-CoV-2 infection." (PMID 34210280, 2021). "Preexisting immunity in the form of cross-reactive memory CD4+ T cells affected immune responses to the mRNA COVID-19 vaccine in this cohort." (PMID 34519540, 2021). "Pediatric COVID-19 patients had marked proliferation in CD4+ T cells, with a similar range of Ki67+ CD4+ T cells as adult COVID-19 patients." (PMID 33653907, 2021). "For CD4+CD154+CD137+ reactive T cells seven out of eight post COVID-19 Ab− had a T cell response to the spike N- and C-terminal domain of SARS-CoV-2." (PMID 34322120, 2021). "Patients with COVID-19 display lymphopenia (CD4+ and CD8+ T lymphocyte deficiency) and reduced interferon (IFN)-γ expression in CD4+ T lymphocytes, which are responsible for the severity of COVID-19." (PMID 34360684, 2021). "Analysis of SARS-COV-2 specific adaptive immune responses during acute COVID-19 identified coordination between SARS-COV-2-specific CD4+ T cells and CD8+ T cells in limiting disease severity." (PMID 34394127, 2021). "Laboratory tests show that the number of lymphocytes is significantly reduced in COVID-19 patients; in particular, the levels of CD4+ T and CD8+ T cells in patients with severe disease show a significant and progressive decline." (PMID 33995341, 2021). "Analysis of circulating SARS-CoV-2-specific CD8+ and CD4+ T cells in blood samples from COVID-19 patients revealed the immunodominance pattern for M, S, and N proteins, each recognized by 100% of COVID-19 cases studied." (PMID 34066920, 2021). "Our data showed that SARS-CoV-2–responding CD4+ T cells were qualitatively different in acute COVID-19 cases compared with uninfected individuals." (PMID 33945513, 2021). "In the group of acutely infected COVID-19 patients, all but one patient recognized at least two peptide specificities of the N protein with an average number of 12.44 (range 0–19; median 16) CD4+ T cell responses." (PMID 34529740, 2021). "Compared to non-COVID-19, we observed slightly less CD4+ TH17-cells, but more TH1-like-cells in COVID-19." (PMID 33473155, 2021). "In severe COVID-19 cases the T-cell response is dominated by spike-specific CD4+ T cells, and as consequence of T-cell and B-cell collaboration high numbers of neutralizing high-affinity-antibodies are detected." (PMID 34223911, 2021). "We observed sustained increase of programmed cell death 1 (PD-1) in COVID-19 patients compared with healthy donors in both CD4 and CD8 compartments." (PMID 33361110, 2021). "The authors documented SARS-CoV-2 specific CD4+ T-cell and antibody responses in all analyzed COVID-19 cases." (PMID 33918624, 2021). "In the COVID-19, Th1 cells were significantly higher than Th2 CD4+ T cells, which produced IL-4, IL-2, and TNF, main markers for Th2 response." (PMID 34571855, 2021). "In the early phase of COVID-19, activated peripheral blood CD4+ and CD8+ T lymphocyte fractions arise in the circulation." (PMID 34680460, 2021).
COVID-19 (continued). "This was also observed in our cohort, in which patients suffering from different severity of COVID-19 displayed different levels of circulating CD4+ T cell subsets." (PMID 34925369, 2021). "Other studies showed that in moderate and severe COVID-19 cases characterized by lymphopenia there was a drastic reduction in the numbers of both CD4+ and CD8+ T cells." (PMID 33741972, 2021). "SARS-CoV-2 infection mainly affects T lymphocytes especially CD4+ and CD8+ T cells, which were significantly decreased and associated with disease severity in COVID-19." (PMID 34282057, 2021). "Mean levels of CD4+T cells increased from 910.7 at baseline to 1000.2 cells/μL after the second dose of the COVID-19 vaccine in the ABB C1® group, whereas there was a decrease from 1055.1 to 929.8 cells/μL in the placebo group." (PMID 34959898, 2021). "Within the clonally expanded CD4+ T cell compartment, we observed overall decreased CD4-GZMB and increased Th1-, Th2-, Th17-, and cycling CD4+ T cell proportions from COVID-19 patients versus controls." (PMID 35095917, 2021). "Patients with severe COVID-19 are more likely to exhibit lymphopenia on admission, resulted in a broad immune cell reduction including CD4+ and CD8+ T cells, NK cells, and monocytes and dendritic cells." (PMID 34737699, 2021). "On the contrary, the reduction of peripheral lymphocytes, including CD3+, CD4+, and CD8+ T cells, has been associated with COVID-19 severity and outcome." (PMID 34771446, 2021). "Our data showed that poor immunological response was associated with significantly lower S-RBD-IgG levels, suggesting that the impaired humoral response of COVID-19 vaccine in PLWH is possibly related to CD4+ T cell counts." (PMID 34960204, 2021). "Most interestingly, exosomes of MILD COVID-19 patients were more efficient in stimulating CD4+ T-cell growth compared to those of SEVERE COVID-19 patients." (PMID 35111156, 2021). "The presence of robust SARS-CoV-2-specific CD4+ and CD8+ T-cell responses has been associated with lower COVID-19 severity, and seems to contribute in resolving acute disease." (PMID 35111162, 2021). "On the other hand, CD4+ T cellular functionality is also impaired in critically ill COVID-19 patients: there is a significant reduction of IFN-γ producing CD4+ T cells." (PMID 33810287, 2021). "To decipher the functional consequences of FoxP3 overexpression in Tregs from severe COVID-19 patients, we generated 86 RNA-sequencing (RNA-seq) transcriptome profiles, passing quality thresholds, of blood Treg (CD4+CD25hiCD127lo) or Tconv (CD4+CD25−)." (PMID 34433692, 2021). "The immuno-phenotypic analysis performed by multi-colour flow cytometry confirmed that patients suffering from severe COVID-19 harboured significantly reduced circulating T cell subsets, especially for CD4+ T, Th1, and regulatory T cells." (PMID 34925369, 2021). "The CD4 cell counts before diagnosis of COVID-19 were available in only 844 out of 6235 cases; the nadir CD4 cell count ranged from 97 to 434 in these cases." (PMID 33808066, 2021). "Increase in the CD4+ Tregs has been previously reported through flow cytometry experiments in the blood of COVID-19 patients." (PMID 34721400, 2021). "This study found that SARS-CoV-2 S-specific reactive CD4 + T cells exhibited a higher frequency than CD8+ T cells in recovered COVID-19 patients, with a greater number of corresponding epitopes presented." (PMID 34805136, 2021). "Older COVID-19 patients have also exhibited graver cases of lymphopenia, which affects CD4+ T cells, CD8+ T cells, natural killer cells (NKCs), and B cells." (PMID 34681059, 2021). "Another study which analysed T cells in 66 recovered COVID-19 patients, found that CD4+ T cell count was predictive of the duration of viral RNA detection in the stool sample." (PMID 35965490, 2021).
COVID-19 (continued). "On average T cells specific for the different structural proteins (NP, M and Spike) within 2–3 months from COVID-19 recovery are present at 0.1–1% of total CD4 or CD8 T cells with methods that detect T-cell AIM." (PMID 38626271, 2021). "COVID-19 progression to a severe clinical picture is related to the depletion of several immune cell types, including naïve CD4+ and CD8+, and CD56high NK cells." (PMID 34434199, 2021). "During clinical trials, COVID-19 mRNA vaccines were found to induce the maturation of CD4+ and CD8+ T-lymphocytes and more than 70% of vaccinated individuals have memory T-lymphocyte responses." (PMID 35046961, 2021). "Firstly, CD8+ T-cells exhibited good effector functions along their resident-memory and partially-exhausted lineages in mild COVID-19, while also CD4+ T-cells showed disease-resolving functions in TH1- and TH17-lineages." (PMID 33473155, 2021). "An elevation was observed in the numbers of activated CD4+ cells, antibody-secreting cells, as well as IgM and IgG titers in the blood of mild COVID-19 patients which persisted for at least 7 days after recovery." (PMID 34766001, 2021). "In the current study, we utilized class II tetramer reagents for epitope identification and examined SARS-CoV-2-specific CD4+ T cells in both COVID-19 convalescent individuals (exposed) and pre-December 2019 SARS-CoV-2 naïve individuals (unexposed)." (PMID 34965282, 2021). "Among others parameters, mild and severe forms of the COVID-19 are characterized by a marked decrease in the total number of peripheral blood lymphocytes including T cells, both CD4+ and CD8+, B lymphocytes and Natural Killer (NK) cell." (PMID 33718270, 2021). "The knowledge on implication of cross-reactive CD4+ T cells in the disease outcome and in establishment of immunological memory is crucial for the development and implementation of COVID-19 vaccines." (PMID 33777028, 2021). "There were not any differences in the median proportion of CD45RO+ CD4+ cells between the three groups, but when we analyzed the median of CD4+ CD45RO+ GMF intensity we observed the lowest proportion in COVID-19(+) patients." (PMID 33419040, 2021). "To study the possible alterations of Th subsets, we first determined the relative number of CD3+CD4+ cells in the peripheral blood of both COVID-19 groups and in the healthy donors." (PMID 34696395, 2021). "Specifically, patients with symptomatic COVID-19 displayed reduced numbers of CD4+ and CD8+ T-cell subsets including naïve, central memory, and effector memory cells." (PMID 33821263, 2021). "Patients with comorbidities were prone to severe COVID-19, and the decreased T cell, CD4+ T cell and B cell counts were closed related to severe COVID-19." (PMID 34210280, 2021). "We have shown that OTD subjects have increased numbers of highly functional SARS-CoV-2 specific T cells, particularly CD4+ T cells, compared with hospitalized patients with severe COVID-19." (PMID 34858405, 2021). "Dysregulation of the PD-L1 gene correlates with substantial phenotypic differences between COVID-19 cases and controls, predominantly in monocytes, gamma delta T cells, neutrophils and CD4+ interferon-stimulated T cells." (PMID 34163490, 2021). "CD4+ T lymphocytes producing IFN-γ were the principal phenotype for memory T cells after virus exposure in COVID-19 and can be the key for vaccine development and protective evaluation, as well as the IFNG expression with antiviral genes." (PMID 34571855, 2021). "Patients with COVID-19 have been shown to have significantly reduced CD4+, CD8+, and total T-cell counts." (PMID 34940403, 2021). "One of the prominent immunological features among severe COVID-19 patients was lymphopenia with decreased CD4+, CD8+ T, and Treg cells." (PMID 34373739, 2021). "In this regard, SARS-CoV-2-specific HLA-DR+ Ki-67+ PD-1+ CD4+ T cells are observed in COVID-19 patients." (PMID 35126355, 2021).
COVID-19 (continued). "To assess the impact of age on SARS-CoV-2–cross-reactive T cell immunity, we examined SARS-CoV-2 spike–specific CD4+ T cell responses in 568 unexposed individuals and 174 COVID-19 convalescents." (PMID 34465633, 2021). "Our results showed increased percentage of T cells in COVID-19 patients exclusively in effector memory (CD62L-CD45RA-) subsets within both CD4+ and CD8+ T cell compartments." (PMID 33692788, 2021). "Previous studies reported an increase in tumor necrosis factor (TNF)-α and interferon (IFN)-γ production by CD4+ T cells after AstraZeneca-Oxford COVID-19 vaccine." (PMID 35004790, 2021). "The reduced lymphocyte and CD4 + T cell count indicates that COVID-19 inhibits immune cell function by consuming the cells." (PMID 34514172, 2021). "Although COVID-19 patients have decreased CD4+ and CD8+ T cells, increased IL-6 and IL-10 levels, associated with cytokine storm, are linked to disease severity." (PMID 34244584, 2021). "Th1 and Th17 CD4+ T cells are also thought to play a role in the inflammatory and antiviral responses, which has been observed in COVID-19 infected patients." (PMID 34359987, 2021). "The severe COVID-19 patients had the lowest diversity of CD4+ T cell clonotypes among all studied groups." (PMID 35095917, 2021). "In conclusion, the CD4+/CD8+ T cell ratio was lower in patients with severe COVID-19 compared to those with mild/moderate form of disease." (PMID 33937149, 2021). "For example, it has been reported that Tregs (CD3+ CD4+ CD25hi CD127lo FoxP3+) in PBMCs were markedly decreased in severe COVID-19 patients 59-61." (PMID 33907514, 2021). "A previous study showed that the decline of CD8+ T cell count is greater than count of CD4+ T cell, and the decline in the former is positively related with poor prognosis of patients with COVID-19." (PMID 34725309, 2021). "In the early phase of COVID-19, a dramatic decrease of CD4+ T cells is observed, which correlates with COVID-19 severity." (PMID 35126355, 2021). "Spike-specific memory CD4+ T cell frequencies were also similar between low-dose mRNA-1273 vaccinated persons and COVID-19 cases." (PMID 34519540, 2021). "This is in line with recent studies reporting that SARS-CoV-2–specific CD4+ T cell responses predominate over CD8+ T cell responses and that CD4+ T cell cytopenias are a characteristic change in severe COVID-19." (PMID 33461503, 2021). "The persistence of CD4+ Tem cells in circulation over time after COVID-19 recovery indicates that the virus-specific antibody levels can be maintained, conferring protection against re-infection." (PMID 34452355, 2021). "This means patients with severe COVID-19 have markedley lower absolute number of T lymphocytes, CD4+T and CD8+ T cells." (PMID 34036149, 2021). "Using a whole-blood assay, we investigated the SARS-CoV-2– and M. tuberculosis–specific CD4+ T cell response in hospitalized COVID-19 (n = 95) and non–COVID-19 patients (n = 38)." (PMID 33945513, 2021). "A higher percentage of CAP patients showed reduced CD3+, CD3+CD4+, reduced CD16+CD56+, reduced CD4+/CD8+ ratio, increased CD19+%, and normal CD3+CD4+% compared with the COVID-19 patients." (PMID 34150910, 2021). "Further investigation into the relationship between COVID-19 outcomes and CD4+ T-cell count, HIV viral load, ART and the use of tenofovir disoproxil fumarate is warranted." (PMID 33587448, 2021). "Post COVID-19 Ab− (p = 0.018) and Ab+ (p = >0.0001) had significantly higher frequencies of tp activated CD4+ T cells compared to HC." (PMID 34322120, 2021). "The immune response of patients with fatal severe COVID-19 is hypofunctional with the reduced number and dysfunction of CD4+ and CD8+ T cells." (PMID 33995364, 2021). "By analyzing dynamic changes of lymphocyte subsets after symptom onset, we found that the percentage of CD19+ B cells and CD4+ T cells was generally higher in female patients during the disease course of COVID-19." (PMID 34225644, 2021).